IL1B (interleukin 1 beta)
Diseases named in the same sentence as IL1B in open-access papers (continued):
Sharing a sentence is not in itself a finding about the gene and the disease.
COVID-19 (continued). "In stroke patients with COVID-19, the cytokines IL-1β, IL-6, and TNF-α are representative as well as in the CSF and blood serum." (PMID 34577633, 2021). "Metformin also blocks IL1β production and increases the anti-inflammatory cytokine IL-10 and inhibits complex 1 in mitochondria, indicating its anti-inflammatory potential for COVID-19." (PMID 34240083, 2021). "Specifically, Lee and colleagues reported that type I interferon and tumor necrosis factor alpha (TNF-α)/IL-1β correlated with COVID-19 severity." (PMID 34319784, 2021). "In patients with severe COVID-19, high levels of circulating IL-6, IL-1β, INFγ, and TNF-α have been reported, together with an unbalanced white cell formula, consisting of high neutrophils and decreased CD4+ and CD8+ T cells." (PMID 35140702, 2021). "In addition, Panx-1 channel opening is indirectly associated with IL-1β processing and release, suggesting that Panx-1 amplifies inflammation, but its role in COVID-19 pathogenesis is unknown." (PMID 34841222, 2021). "The increased systemic values of TNF-α, IL-1β, IL-6, IL-12, IL-23, and IL-33 support the prevalence of innate pro-inflammatory mediators in the serum of subjects with a severe form of COVID-19." (PMID 34917631, 2021). "The imbalance of the immune system can increase various inflammatory cytokines such as MIP-1, GM-CSF, and IL1β, leading to respiratory injury and accelerating COVID-19." (PMID 34578138, 2021). "For example, intensive care unit COVID-19 patients have the highest concentrations of IL-1β, IL-6, and IL-6 to IL-10 ratio." (PMID 34578898, 2021). "Research into the mechanisms regulating the generation of NETs has shown that, among inflammatory cytokines engaged in the immunopathogenesis of COVID-19 is IL-1β." (PMID 33466589, 2021). "The IFNα/β response is one of multiple responses, including production of IL-6, TNFα, and IL-1b, by innate and adaptive immune cells that have the potential to limit COVID-19 progression." (PMID 34368185, 2021). "Our data that ATP, PGE2, and IL1β are highly concentrated in the BAL obtained from COVID-19 individuals is exciting but needs to be considered carefully due to the fact that during the evolution of the disease, significant apoptosis of lung cells occurs." (PMID 34841222, 2021). "Higher concentrations of IL-1β and IL-12(p70) were detected only in serum from mild COVID-19 patients, while IP-10 only in serum of severe COVID-19 patients, compared to controls." (PMID 34675240, 2021). "As the inflammatory cytokines, IL-1β is upregulated in COVID-19 patients and is secreted through the SARS-CoV-2-induced necroptosis pathway." (PMID 33763078, 2021). "COVID-19 patients were characterized by an increased IL1β, increased lymphoid activation biomarkers, increased TF, and higher fibrinogen, antithrombin, and platelet count." (PMID 35111777, 2021). "Patients with COVID-19 showed high mRNA expression and secretion of cytokines, IL-1β, IL-6, TNF-α, and IL-18, but showed a significant reduction in IL-6 and IL-1β after treatment with nanocurcumin." (PMID 34025433, 2021). "Three studies compared IL-1β levels of COVID-19 patients were included in the network meta-analysis." (PMID 33557779, 2021). "In conclusion, both active AOSD and severe COVID-19 patients showed elevated Gal-3, Gal-9, and cytokines, including IL-1β, IL-1Ra, IL-10, IL-6, IL-18, and TNF-a, supporting a common link of cytokine storm in the pathogenesis of both diseases." (PMID 34367188, 2021). "Pro-inflammatory cytokines and chemokines (IL-6, IL-8, TNF-α, IL-1β) are differentially expressed in COVID-19 patients according to severity." (PMID 34320031, 2021). "In this study, levels of IL-1β, IL-1RA, IL-18, and IL-18BP were higher in patients with COVID-19 than in HVs; however, they were lower than in patients with canonical autoinflammatory diseases." (PMID 33232303, 2021).
COVID-19 (continued). "Consistent with published studies, we observed high concentrations of inflammation-associated cytokines, including IL-6, TNF-α, IP-10, IL-10, IL-1α and IL-1β, in serum and nasal lining fluid from PCR-confirmed COVID-19 patients." (PMID 34117221, 2021). "Our results revealed a stronger positive correlation between serum values of IL-33 and innate immunity mediators TNF-α, IL-1β, IL-6, IL-12, and IL-23 in the severe form of COVID-19." (PMID 34917631, 2021). "In patients with cytokine storm secondary to COVID-19, elevated serum cytokine levels are mainly related to IL-1β, IL-6, CXCL10, TNF-α, IFN-γ, macrophage inflammatory protein (MIP) 1α and 1β, and VEGF." (PMID 33669011, 2021). "Some of these molecules, including IL-6, IL-12, IL-1β and IL-18, also constitute the inflammatory cytokine storm seen in severe COVID-19 cases." (PMID 33917321, 2021). "Plasma levels of IL-6, TNFα, IL-1β, IL-10 and IL-21 were significantly higher in Asymptomatic COVID-19 cases as compared with Controls." (PMID 34824360, 2021). "High levels of proinflammatory cytokines, particularly IL-6, IL-8 and IL-1β, were found in the BALFs of severe COVID-19 patients." (PMID 33912590, 2021). "Serum levels of IL-7, IL-10 and IP-10 were elevated in COVID-19 asymptomatic cases compared to healthy controls, whereas IL-1RΑ, IL-1β, IL-6 and IP-10 were higher in symptomatic compared to asymptomatic COVID-19 patients." (PMID 34603318, 2021). "Severely ill patients hospitalised with COVID-19 exhibit increased levels of Interleukin (IL)-1β, IL-2, IL-6, IL-7, IL-8, IL-10, IL-17, granulocyte colony stimulating factor (G-CSF), monocyte chemoattractant protein 1 (MCP-1) and tumor necrosis factor (TNF)." (PMID 34205262, 2021). "Our results indicated that the IL1β level remained higher in all COVID-19 case groups compared with controls." (PMID 34836309, 2021). "Recently research indicated that suspected sHLH related to COVID-19 received IL-6 antagonistic therapy and Anakinra (recombinant soluble receptor antagonist of IL-1β and IL-1α)." (PMID 33926377, 2021). "These patients had high IL-1β, IL-6 and IL-8 protein levels in BALF, a finding that was reproduced in a study entailing four patients with COVID-19 associated ARDS." (PMID 34054832, 2021). "The high surge of IL6, IL1b, IFNγ, C-reactive protein, and TNF-α senescence leads to lower airway and lung injury and increased risk for COVID-19 in elderly patients." (PMID 33815889, 2021). "As seen in the whole blood transcriptome analysis, leukocytes from COVID-19 patients also demonstrated elevated IL-1β and IL-6 module activity compared with controls, and once again this distinction was not seen in IL1A, IL1B, and IL6 gene expression." (PMID 33319166, 2021). "We attributed the alteration of CD90 activity to the high expression of proinflammatory cytokines, such as IL-1β and TNFα, which are commonly increased in COVID-19 patients." (PMID 34746417, 2021). "Innovative approaches for evaluating the biological activity of these cytokines in vivo are urgently needed to complement clinical trials of therapeutic targeting of IL-1β and IL-6 in COVID-19." (PMID 33319166, 2021). "Namely, the inhibition of IL-1β deserves consideration for patients with COVID-19 presenting with myocardial injury due to its anti-inflammatory activity." (PMID 33404925, 2021). "In mild COVID-19, the cytokines weakly elevated in patients with asthma were IL-1β, IL-13, CXCL5, and LF." (PMID 34238349, 2021). "An elevated level of immunomodulatory cytokines, including IL-1α, IL-1β, IFN-α, IL-17A, and IL-12p70, constitute COVID-19 signature that exhibits dynamic features associated with clinical manifestations." (PMID 34912345, 2021). "We also assessed plasma levels of three major proinflammatory cytokines, IL-1β, IL-6 and TNFα, and IL-10, an anti-inflammatory cytokine, in COVID-19-naive older adults." (PMID 34868051, 2021).
COVID-19 (continued). "Plasma levels of IL-1β, IL-1RA, and IL-8, among others, were also increased in patients who recovered from COVID-19." (PMID 34784300, 2021). "The use of aaPRP in severe COVID-19 patients is found to reduce their plasma IL-1β concentration which is beneficial to prevent pulmonary fibrosis after they have recovered." (PMID 34306796, 2021). "Despite showing a variable clinical spectrum, severe COVID-19 patients commonly exhibited shortness of breath, and production of pro-inflammatory cytokines such as IL-6, IL-8, IL-1β, IL-1RA3,56." (PMID 34413339, 2021). "Here, the lower expression of DUSP1 observed in SARS-CoV-2 infected cells and nasopharyngeal swabs of severe COVID-19 patients was associated with the higher expression of TNF-α, IL-1β, and IL-1A genes (respectively)." (PMID 33995033, 2021). "In contrast, IL-1β remained low, suggesting disturbances in inflammasome activation during COVID-19." (PMID 33717195, 2021). "In fact, patients with COVID-19 display a pro-inflammatory (IL-1β, IL-6, IL-7, IL-8, IL-9, FGF, G-CSF, GM-CSF, IFN-ɣ, CXCL10, CCL2, CCL3, CCL4, PDGF, TNFα, and VEGF) and regulatory cytokine profile (IL-10 and TGFβ; cytokine storm)." (PMID 33995342, 2021). "Inflammasomes, are macromolecular inflammatory signalling complexes activated by the detection of pathogenic microorganisms and process pro-inflammatory cytokines (i.e., pro–IL-1β and pro-IL-18) to their bioactive forms, have been investigated in COVID-19." (PMID 33669011, 2021). "We observed that carriers of T/T homozygote at rs8176719 (i.e., individuals of blood group O) tend to have an elevated serum level of IL-1β among COVID-19 patients." (PMID 34465887, 2021). "The latest laboratory findings from Wuhan patients also showed that mild COVID-19 patients had elevated levels of IL-1B, IFNγ, CXCL10, and CCL2, whereas in severe cases, G-CSF, CXCL10, CCL2, and CCL3 were elevated." (PMID 34441862, 2021). "It should be noted that the cytokine profile similar to MAS/sHLH has also been observed in COVID-19 patients, especially the increase of IL1β, IL2, IL6, IL17, IL8, TNF and CCL2." (PMID 34912345, 2021). "We show that in COVID-19, IL-1β and IL-6 cytokine activity is detectable at a site of disease, the nasopharynx, where greater IL-6 bioactivity in particular is associated with higher levels of SARS-CoV-2 detected." (PMID 33319166, 2021). "Increasing MDSCs during the early stages of COVID-19 were correlated with IL-1β, IL-6, IL-8, and TNF-α plasma levels, particularly in patients who required intensive care treatments, suggesting new therapeutic options geared toward MDSCs42." (PMID 34341347, 2021). "COVID-19 is also characterized by a “cytokine storm” with increased levels of pro-inflammatory cytokines in the blood, such as IL-1β, TNF-α, IL-6, IL-12, and we detected increased IL-1β, IL-6, IL-12, IL-23, and IL-27 in the serum following ORN06 aspiration." (PMID 33481950, 2021). "COVID-19 patients have higher serum levels of IL-6, IL-1β, soluble IL-2 R, IL-8, IL-10, IL-17, and TNF-α." (PMID 33757410, 2021). "A prior study of cytokines in a limited COVID-19 cohort study of 40 ICU patients reported IL-1β levels to be elevated above the upper limit of normal." (PMID 34228746, 2021). "Our present results identified obvious elevations of various cytokines in patients with severe COVID-19, including IL-1α, IL-1β, IFN-γ, TNF-α, IL-2, IL-4, IL-6, IL-10, and IL-17A." (PMID 34113636, 2021). "The levels of pro-inflammatory cytokines were significantly higher in the patients with COVID-19 when compared to the healthy control group (Unpaired T-test, p = 0.0001 for IL-1β and p = 0.0003 for IL-6)." (PMID 34443474, 2021). "Analysis revealed a stronger positive correlation between the serum values of IL-33 and TNF-α (p = 0.000), IL-1β (p = 0.000), IL-6 (p = 0.000), IL-12 (p = 0.000), and IL-23 (p = 0.000) in COVID-19 patients with severe disease." (PMID 34917631, 2021).
COVID-19 (continued). "Compared to patients with moderate COVID-19, patients with severe/critical infections have much higher levels of inflammatory cytokines, particularly interleukin IL-6, IL-1β, and TNF-α, in their BALF and lung tissue." (PMID 33468250, 2021). "The identification of IL-1β, IL-6, interferon-γ and IL-16 is an example of cytokines in the COVID-19 network." (PMID 33664395, 2021). "In our study, we found that most of the cytokines recovered in the convalescent individuals except that a significantly higher proportion of COVID-19 convalescent individuals presented with elevated IL-5, IL-6, and IL-1β levels." (PMID 34234102, 2021). "The linear multiple regression model was calculated to predict the levels of IL-33 based on COVID-19 severity, IL-6, IL-1β, IL-12, TNF-α, and IL-23." (PMID 34917631, 2021). "Although these researchers did not specify the subtype of influenza A virus infection, their results coincide with our data with regards to the higher induction of IL-1β in COVID-19 than influenza." (PMID 33995342, 2021). "PPI network for the immunity and inflammation cytokines in COVID-19 among R. crenulata targets showed that IL-10, IL-6, IL-1B, TNF-α, CCL2 and CXCL8 were important nodes in the network." (PMID 34313585, 2021). "Significantly higher concentration of TNF-α (p = 0.001), IL-1β (p = 0.001), IL-6 (p = 0.001), IL-12 (p = 0.001), IL-23 (p = 0.043), and IL-33 (p = 0.001) have been found in the sera of COVID-19 patients with severe disease." (PMID 34917631, 2021). "Our data demonstrated that after being induced by Prot_S, Calu-3 cells showed the upregulation of TNFα, IL6, IL1β, and IFNγ, which is in line with the clinical situation of patients with COVID-19." (PMID 34074129, 2021). "We observed higher caspase-1/4/5 activity within the classical monocyte subset from COVID-19 patients when compared to HCs, suggesting this cell subset contributes to IL-1β and IL-18 maturation during COVID-19." (PMID 35095880, 2021). "The high level of IL-1β in post-COVID vs. HC was particularly remarkable, since patients with acute COVID-19 had relative lower levels of this cytokine than post-COVID-19 and HC subjects." (PMID 34572439, 2021). "IL-1β and IL-1Ra levels were significantly higher in COVID-19 patients and active AOSD patients compared with HC, but there was no significance in IL-1β or IL-1Ra levels between COVID-19 and active AOSD patients." (PMID 34367188, 2021). "IL-1β is a main cytokine released during pyroptosis, and its enhancement can be observed in patients with COVID-19." (PMID 33404925, 2021). "It is also possible that SARS-CoV-2 activates the inflammasome, as high levels of IL-1β have been observed in COVID-19 patients." (PMID 33995342, 2021). "Severe patients have significantly elevated levels, and one study found high levels of IL-1β persistent in COVID-19 patients up to 4 weeks after symptom onset—similar to IL-6." (PMID 34575258, 2021). "Our results showed that critically ill COVID-19 patients had increased serum levels of IL-1β, IL-1RA, IL-6, IL-9, and CXCL10, and lower levels of IL-2 and IL17A as compared to healthy volunteer donors." (PMID 33995342, 2021). "Recent published studies have reported that elevated inflammatory cytokine (such as TNFα, IL-1β, IL-6, IL-10, IL-17, IL-18, and IFNγ) levels were seen in active COVID-19 cases compared to healthy donors." (PMID 34348897, 2021). "In COVID-19 patients a pro-inflammatory status with high levels of IL-6, IL-1B and TNF-α has been demonstrated." (PMID 34313585, 2021). "Our COVID-19 patients had significantly higher levels of IL-1β, IL-1Ra, IL-10, IFN-α2, IL-6, IL-18, and TNF-α than HC." (PMID 34367188, 2021). "Compared to healthy controls, CD16+ monocytes from people with COVID-19 had significantly upregulated expression of genes involved in inflammation including cytokines and chemokines, such as IL-1β, CXCL8, CCL3 (MIP-1α), and CCL4 (MIP-1β)." (PMID 34108966, 2021).
COVID-19 (continued). "We found a significantly higher serum concentration (p < 0.05) of TNF-α, IL-1β, IL-6, IL-12, IL-23, and IL-33 in patients with COVID-19 with severe disease." (PMID 34917631, 2021). "Our data also support the use of specific NLRP3 inhibitors, such as MCC950, to attenuate inflammasome-related responses during COVID-19, since this drug was able to abrogate ex-vivo IL-1β secretion, conversely to colchicine, which decreased TNF-α release." (PMID 35095880, 2021). "This predictive model assembling severe COVID-19-related proteins supports a role for known contributors to the cytokine storm such as IL1β, IL6, TNFα, JAK2, but also less prominent actors such as IL17, IL23 and C5a." (PMID 34293006, 2021). "We also noted that similarly to HIF-1α, the level of IL-1β mRNA was much higher in PBMCs of COVID-19 patients related to healthy individuals." (PMID 34408131, 2021). "Analyses performed in the BAL fluids showed that the chemokines CCL3 and CCL5 and the proinflammatory molecules IL-1β and IL-6 were significantly higher in patient 1 compared to the non-COVID-19 bLTx patient." (PMID 33801959, 2021). "As for critical COVID-19 patients, their plasma IL-1β concentration increased but one of the patients recovered from COVID-19." (PMID 34306796, 2021). "When we analyzed the median proportion of selected cytokines levels (pg/mL) such as: IL-1β, IL-4, IL-5, IL-6, IL-8, IL-10 and TNFα, we observed significant difference between severe COVID-19 and critical COVID-19 patient only for IL-6 level." (PMID 34064802, 2021). "The cytokine profiling of COVID-19 patients in our study provided further evidence that the CRS-associated cytokines, such as IL-6, IL-1β, IL-10, IL-18, and IFN-γ, were dramatically elevated in severe patients." (PMID 33712622, 2021). "In severe COVID-19 lung macrophages displayed high expression of IL-1β, IL-6, TNF-α and various chemokines (CCL2, CCL3, CCL4, CCL7, CXCL9, CXCL10 and CXCL11)." (PMID 34054832, 2021). "Cytokine profiles observed in COVID-19 patients have revealed increased levels of IL-1β, IL-2, IL-6, and TNF-α and increased NF-κB pathway activity." (PMID 33927728, 2021). "Secretion of IL-1β is also a characteristic of COVID-19 and since this cytokine is instrumental in the recruitment of monocytes, secretion by our model is a valuable characteristic." (PMID 34152044, 2021). "An excessive amount of pro-inflammatory cytokines, including tumor necrosis factor-alpha (TNF-α), interleukin (IL)-1β, and IL-6, has been reported in most COVID-19 patients." (PMID 33708378, 2021). "COVID-19 increases plasma secretion of interleukin 1β (IL-1β), interferon γ (IFN-γ), interferon-γ-induced protein 10 kDa (IP-10), monocytic chemoattractant protein-1 (MCP-1), IL-4, and IL-10." (PMID 33946649, 2021). "Co-staining with CD163 revealed that proinflammatory cytokines IL-1β, IL-6, and IL-18 were more highly expressed in the pulmonary macrophages of COVID-19 patients than in those of control donors." (PMID 34960782, 2021). "Critical COVID-19 is distinguished by very high levels of IL-1β and T lymphocyte activation (including IL-7), whereas septic shock displays higher levels of IL-6, IL-8 and a more significant myeloid response (including TREM-1 and IL-1ra)." (PMID 35111777, 2021). "Individuals with COVID-19 have been reported to have high levels of major inflammatory cytokines such as IL-6, IL-1β, and TNF-α in the circulation, which was associated with the magnitude of disease severity." (PMID 33959020, 2021). "IL-1 beta (IL-1β), which is a main activator of IL-6 expression, has attracted our attention in the exploration of COVID-19 therapies." (PMID 33404925, 2021). "In relation to COVID-19, IL-37 has been suggested to be a potential treatment based on its anti-inflammatory profile to inhibit IL-1β, IL-6 and TNF, which are the main players of the cytokine storm." (PMID 34422917, 2021).